CFTR (CF transmembrane conductance regulator)
Diseases named in the same sentence as CFTR in open-access papers (continued):
Sharing a sentence is not in itself a finding about the gene and the disease.
pancreatitis (103 papers, 2008 to 2026). Inflammation of the pancreas. "In this large cohort of women tested for prenatal carrier screening, CFTR pathogenic variants relevant to pancreatitis were overlooked, despite informing etiology, management, and prognosis." (PMID 40468859, 2025). "CFTR carrier status detected via prenatal screening is associated with increased pancreatitis risk in women, but clinical recognition remains low." (PMID 40468859, 2025). "Only the two patients tested after a pancreatitis panel had clinical recognition of CFTR‐mediated risk." (PMID 40468859, 2025). "CFTR heterozygosity is a reported risk factor when discovered through genetic testing for pancreatitis." (PMID 40468859, 2025). "Seven patients had confirmed pathogenic CFTR variants prior to their pancreatitis diagnosis with a mean of 5 years from genetic testing to pancreatitis diagnosis." (PMID 40468859, 2025). "In this study, we found that women identified as CFTR carriers through prenatal carrier screening have a significantly higher risk of developing pancreatitis." (PMID 40468859, 2025). "We used this model to characterize ductal anion transport and to assess the effect of cytokines typically associated with pancreatitis on CFTR function." (PMID 38262945, 2024). "Loss of CFTR-dependent anion and fluid secretion in the ducts of the exocrine pancreas is thought to contribute to the development of pancreatitis, but little is known about the impact of inflammation on ductal CFTR function." (PMID 38262945, 2024). "In this study, we characterized pancreatic ductal anion (bicarbonate, chloride) transport and assessed the effect of cytokines typically associated with pancreatitis on ductal CFTR function." (PMID 38262945, 2024). "Next Generation Sequencing was performed to analyze a panel of nine genes associated with pancreatitis (CaSR, CFTR, CPA1, CTRC, CTSB, KRT8, PRSS1, PRSS2, and SPINK1)." (PMID 38927485, 2024). "For instance, it was demonstrated that CFTR protein potentiators can reduce the number of pancreatitis attacks in patients with CFTR-associated pancreatitis." (PMID 37389024, 2023). "After PIP score calculation, patients with mild mutations had a greater risk of developing pancreatitis than those with moderate or severe CFTR genotypes." (PMID 36832409, 2023). "The purpose of this research is to provide a description of the disease-causing variations of the CFTR gene that are now elevating the risk of pancreatitis in the Puerto Rican pediatric population." (PMID 36832409, 2023). "Our study cohort of 12 Puerto Rican pediatric patients demonstrated the presence of CFTR variants causing recurrent pancreatitis and EPI in Puerto Rico." (PMID 36832409, 2023). "A published systematic study of 277 EPS with CF participants with or without pancreatitis demonstrated that the risk of developing pancreatitis was linked to the severity of the CFTR genotype." (PMID 36832409, 2023). "As well as genotype being a key determinant, risk of pancreatitis is also amplified in the context of cigarette or alcohol use, both of which independently decrease CFTR function." (PMID 35832587, 2022). "CP-associated variants in the CFTR genes were sought in PubMed using a keyword search (i.e., CFTR plus pancreatitis plus variant or CFTR plus pancreatitis plus mutation; the latest search was performed on 12 April 2022)." (PMID 35974416, 2022). "Mutations in PRSS1, SPINK1, CTRC, CASR, and CFTR were linked with pancreatitis and pancreatic cancers when the molecular basis of pancreatitis was investigated." (PMID 36434531, 2022). "Children diagnosed with pancreatitis who were exposed to smoke and had CFTR mutations were admitted to the hospital more often than children without CFTR mutations." (PMID 35011616, 2021). "The past decade saw great advances in understanding the genetics of pancreatitis, including the role of CFTR mutations." (PMID 35011616, 2021).
pancreatitis (continued). "CFTR as a genetic risk factor for AP and chronic pancreatitis was linked with trypsin activation and survival in pancreatitis patients." (PMID 34768335, 2021). "It later became obvious that, unlike in CF, mainly patients with exocrine pancreatic sufficiency and carriers of CFTR mutations with maintained residual CFTR function develop pancreatitis." (PMID 33682322, 2021). "In CF and in hereditary forms of pancreatitis due to mutations in genes other than CFTR (such as PRSS1), genetics are dominant, and environmental factors have little influence on disease onset or severity." (PMID 35011616, 2021). "There are over 2000 variants in the CFTR gene and involvement in pancreatitis or other CFTR-related disorders of several of them remains controversial." (PMID 34065437, 2021). "Some attempts have been made to elucidate the underlying mechanism of pancreatitis under impairment of the CFTR experimentally." (PMID 33682322, 2021). "In this context, it has been reported that pancreas divisum acts as modulator of pancreatitis risk in carriers of additional genetic variants such as the one described here in the CFTR gene." (PMID 32425982, 2020). "Recently, the p.N34S mutation was found in 20% of patients carrying the functionally defective TRPV6 variants, suggesting that the combination of mutated TRPV6 and SPINK1 p.N34S results in predisposition to pancreatitis, as well as the CFTR gene." (PMID 33375361, 2020). "In summary, we found that one out of 28 (3.6%) and 15 out of 28 (53.6%) Japanese patients with paediatric pancreatitis had a pathogenic and functionally affected variant in CFTR, respectively." (PMID 30992994, 2019). "In the present study, the frequency of pathogenic and functionally affected CFTR variants in Japanese paediatric patients with pancreatitis was 1/28 (3.6%) and 15/28 (53.6%), respectively." (PMID 30992994, 2019). "The cystic fibrosis transmembrane conductance regulator (CFTR) gene has been reported as one of the pancreatitis susceptibility genes." (PMID 30992994, 2019). "Many cohort studies examining the association between CFTR variants and pancreatitis have been conducted in western countries." (PMID 30992994, 2019). "A large number of CFTR mutations and the presence of specific CFTR genotype are associated with pancreatitis." (PMID 26100556, 2015). "Common tag-SNPs at the CFTR locus were previously excluded in a pancreatitis genome-wide association study (all p values ≥0.01), suggesting that the missing heritability and predicted dysfunction was primarily associated with multiple rare variants." (PMID 25033378, 2014). "Second, using this panel of 81 CFTR variants, we genotyped the deeply phenotyped North American Pancreatitis Study 2 (NAPS2) subjects to identify candidate CFTRBD variants that were also present in our cases and controls (43 of them)." (PMID 25033378, 2014). "We genotyped 984 well-phenotyped cases of pancreatitis from NAPS2 for 81 CFTR variants, including common CF mutations and variants previously reported in at least two subjects with pancreatitis but not CF." (PMID 25033378, 2014). "Specific CFTR genotypes are significantly associated with pancreatitis and paradoxically genotypes associated with otherwise mild phenotypic effects have a greater risk." (PMID 23883480, 2013). "Mutations in CTRC (chymotrypsinogen C) and CFTR (cystic fibrosis transmembrane receptor) have also been associated with increased risk for pancreatitis." (PMID 22216129, 2011). "The present report focuses on the finding of a new heterozygous mutation in the PRSS1 gene, associated with p.F508del mutation in CFTR, in a child presenting acute recurrent pancreatitis." (PMID 20950468, 2010). "Chronic or recurrent pancreatitis in children should raise suspicion for CFTR mutations, despite a normal sweat test or the presence of an existing diagnosis of pancreas divisum." (PMID 18501000, 2008).
pancreatitis (continued). "In addition to trypsin-related pathways, ductal dysfunction also contributes to pancreatitis risk, particularly through defects in the cystic fibrosis transmembrane conductance regulator (CFTR)." (PMID 41510163, 2026). "Individuals with recurrent pancreatitis or other CFTR‐related conditions should be referred to an accredited CF center for broader evaluation, to identify CFTR variants, as well as quantify CFTR function via sweat chloride testing, NPD, or ICM." (PMID 41536752, 2026). "Among the 11 CFTR carriers who developed pancreatitis, one (9.1%) carried a residual function variant, and 10 (91%) had minimal function variants vs. 14.9% of the overall cohort; this difference was not statistically significant (Fisher's exact test, p > 0.05)." (PMID 40468859, 2025). "Identifying pathogenic CFTR variants in patients with pancreatitis clarifies etiology, enables timely diagnosis, and guides management—potentially including CFTR modulators (e.g., ivacaftor), which are currently only approved for patients with formal diagnoses of CF." (PMID 40468859, 2025). "Therefore, we cannot exclude the possibility of undetected second CFTR variants, modifier alleles, or other pancreatitis‐associated gene variants (i.e., SPINK1, PRSS1, or CTRC)." (PMID 40468859, 2025). "These so-called CFTR modulator drugs improved biomarkers of exocrine pancreas function and may reduce the risk of pancreatitis in CF patients." (PMID 38262945, 2024). "The association between CFTR mutations or polymorphisms and PD might explain why the occurrence of both PD and CFTR mutations may develop into pancreatitis." (PMID 37773168, 2023). "Cystic Fibrosis Transmembrane Conductance Regulator (CFTR) gene mutations in pancreatitis." (PMID 37420288, 2023). "As a result, adolescents may be at risk of complications of CFTR dysfunction, such as pancreatitis, in Puerto Rico." (PMID 36832409, 2023). "Patients with recurrent pancreatitis (pancreatic sufficient patients) treated with CFTR modulators, may have a reduced risk of symptomatic pancreatitis." (PMID 36678791, 2023). "However, as the age of survival continues to rise, there is an increased risk of malignancy in the gastrointestinal and biliary tracts for patients with CFTR variants associated with an increased risk of pancreatitis." (PMID 36832409, 2023). "Furthermore, recent studies demonstrated that not only genetic mutations but other pancreatitis-causing insults, such as alcohol, smoking, or bile acids, can inhibit CFTR-dependent epithelial functions." (PMID 36609875, 2023). "However, little attention was given to the risk of pancreatitis to either parents or PCPs/GPs despite this being one of the conditions most well characterized as a CFTR-related disorder." (PMID 35076474, 2022). "CFTR mutations that preserve residual pancreatic function significantly increase the severity of experimental pancreatitis—mostly via impairing duct cell function and a shift towards a pro‐inflammatory phenotype, not by rendering acinar cells more susceptible to pathological stimuli." (PMID 33682322, 2021). "Consequently, the CFTR alleles that confer an increased risk of developing pancreatitis at the population level only have a small effect on the individual risk." (PMID 35011616, 2021). "The aetiology of paediatric pancreatitis, which includes infections, systemic diseases, trauma, drug induction, biliary system diseases, anatomical abnormalities and genetic cause (CFTR, PRSS1, SPINK1, CTRC mutations), is significantly different from that of adults." (PMID 34178894, 2021). "Pancreatitis may not only be linked to CFTR mutations but may also result from environmental factors that reduce (wild-type) CFTR function." (PMID 35011616, 2021). "In this particular case, the combination of factors associated with pancreatitis (pancreas divisum and the genetic change in CFTR) and the pathogenic variant in NF1 may have had a synergistic role to increase the risk for occurrence of multiple tumors." (PMID 32425982, 2020).
pancreatitis (continued). "Unlike hereditary pancreatitis due to mutations in genes that regulate exocrine pancreas homeostasis, such as CFTR, somatic CNAs that predispose to chronic inflammation and pancreatitis remain unknown." (PMID 32541668, 2020). "Thirteen to thirty seven percent of pancreatitis patients are heterozygous for CFTR mutations." (PMID 32425982, 2020). "The CFTR pathogenic or functionally affected variants found in this study may affect pancreatitis in Japanese populations as well." (PMID 30992994, 2019). "Surveying CFTR gene variants in a Japanese sample could help identify pancreatitis risk in these children." (PMID 30992994, 2019). "Thus, the trans-heterozygosity for mutations in the CFTR and in other genes represents a risk factor for pancreatitis even in patients with CF, as we recently demonstrated for patients with idiopathic RP/CP." (PMID 30134826, 2018). "While mutations in the PRSS1 cause chronic pancreatitis on their own, the SPINK1 mutation is instead likely to act as a disease modifier, lowering the threshold for an individual developing pancreatitis from other genetic factors such as the CFTR mutations and environmental factors." (PMID 29515728, 2017). "(v) Lastly, heterozygous carriers of CFTR mutations have increased risk to develop pancreatitis." (PMID 27382190, 2016). "Using the patchclamp technique, they found that CFTR may be the cause of disturbed secretion of bicarbonates and increased risk of pancreatitis." (PMID 26100556, 2015). "We hypothesized that CFTR variants that disrupt the WNK1-SPAK-associated increase in bicarbonate permeability will increase the risk of pancreatitis and affect other organs in which CFTR is used for bicarbonate secretion." (PMID 25033378, 2014). "The relationship between the severity of the CFTR genotype and the risk of pancreatitis has been well established and it occurs almost exclusively in patients with CF presenting with mild mutations and pancreatic sufficient patients with CF, and not in patients with pancreatic insufficiency (PI)." (PMID 23883480, 2013). "Consistent with the concept that ductal CFTR has an essential tissue-protective role in the pancreas by containing the risk of tissue damage upon exposure to pathogenic stimuli, it was proposed that a reduction in ductal fluid secretion initiates and/or propagates some acute forms of pancreatitis." (PMID 38262945, 2024). "Genetic abnormalities, such as SPINK1, PRSS1, and CFTR gene mutations, are the main risk factors for symptomatic PD in children, and these genetic variants lead to the blockage of the pancreatic duct due to highly viscous pancreatic secretions, inducing pancreatitis in children with PD." (PMID 34796156, 2021). "Whether the pancreatitis‐only phenotype is due to mutations (or compound heterozygous combinations of mutations) that confer a milder defect in CFTR function or whether pleotropic and modifier effects determine the pancreatitis phenotype is still being debated." (PMID 33682322, 2021). "Consequently, as with SCT, the counseling will have to be timed appropriately and target the carrier when risk factor mitigation could be valuable and CFTR modulators potentially useful for severe disorders like pancreatitis." (PMID 32276344, 2020). "One mechanism of which a CFTR mutation could cause pancreatic cancer is by the defect of CFTR and ion transport leading to dysregulated mucus secretion and obstruction of the pancreatic ducts, which all are events that could result in pancreatitis." (PMID 33178018, 2020). "Surveying variants of the CFTR gene might help determine risk of pancreatitis in Japanese children." (PMID 30992994, 2019). "Of great interest, the CS-induced CFTR dysfunction was also found in extrapulmonary disorders that are characterized in CF, such as pancreatitis, male infertility, and cachexia, suggesting that cigarette smoke could cause systemically impaired CFTR, probably via a circulating agent." (PMID 29849907, 2018).
pancreatitis (continued). "Recent data demonstrate that CFTR carriers are more likely to develop CF‐related conditions than a matched cohort, including pancreatitis." (PMID 41536752, 2026). "These clinical manifestations are captured by pharmacodynamic anchors such as faecal elastase-1, steatorrhoea, pancreatitis burden and glycaemic control, providing clinically meaningful benchmarks for CFTR-targeted therapies." (PMID 41683706, 2026). "Following a gastrointestinal workup showing no other etiology for their pancreatitis, these individuals were referred to our clinic to assess for CFTR dysfunction as a potential etiology of their pancreatitis." (PMID 41536752, 2026). "Testing for pancreatitis-associated genetic mutations was performed in eleven patients (2.7%), with only one positive result carrying the CFTR (cystic fibrosis transmembrane conductance regulator) gene mutation." (PMID 41010923, 2025). "For example, gain-of-function mutations in the cystic fibrosis transmembrane conductance regulator (CFTR) gene and cationic trypsinogen gene (PRSS1) are commonly associated with the development of pancreatitis." (PMID 41378273, 2025). "Studies showed that other causes of pancreatitis such as alcohol and tobacco inhibit CFTR function and that in pancreatitis the levels of CFTR expression and its function are diminished." (PMID 39996177, 2025). "Genetic factors, including mutations in the cystic fibrosis transmembrane conductance regulator gene (CFTR) and cationic trypsinogen gene (PRSS1), are rare causes of pancreatitis." (PMID 40376315, 2025). "Due to that previously exposed, it is suggested that impairment of CFTR is critical in the development of pancreatitis." (PMID 39996177, 2025). "Chart review corroborated all pancreatitis diagnoses in CFTR carriers and demonstrated that carrier screening results were never used for diagnostic refinement." (PMID 40468859, 2025). "Our findings indicate that CFTR carriers identified via screening are more likely to have pancreatitis." (PMID 40468859, 2025). "A phenome‐wide association study (PheWAS) was performed to identify additional phenotypic associations, and manual chart review was conducted to evaluate recognition and clinical application of CFTR carrier status in patients diagnosed with pancreatitis." (PMID 40468859, 2025). "While only a small proportion of CFTR carriers develop pancreatitis, a significant subset of patients with pancreatitis were found to be CFTR carriers." (PMID 40468859, 2025). "Among patients with pancreatitis referred for genetic testing, monoallelic CFTR PVs were most frequently identified followed by monoallelic SPINK1." (PMID 39172977, 2024). "Our data are consistent with studies that point towards a more central role of CFTR dysfunction in the pathophysiology of pancreatitis, which indicate that, for some forms, anion secretory defects in the ductal compartment precede acinar pathology." (PMID 38262945, 2024). "Individuals who underwent germline multigene testing for pancreatitis susceptibility genes (CASR, CFTR, CPA1, CTRC, PRSS1, SPINK1) through a large commercial laboratory between 2017 and 2022 were included." (PMID 39172977, 2024). "As recommended by CF Foundation guidelines, in pediatric cases, close monitoring and serial clinical evaluations will help us understand and detect EPI and recurrent pancreatitis in populations with less common CFTR genetic mutations, such as in Puerto Rico." (PMID 36832409, 2023). "The CNVs of CFTR in pancreatitis were also rarely studied, and an anomaly was once reported by Sofia et al5 in 1 of their 80 CP patients." (PMID 37823318, 2023). "The novel mutations mapped in LPL, CFTR, CTRC, and PHKB genes show a potential for new finding in pancreatitis and their clinical-genetic importance for diagnostic and pharmaceutics." (PMID 37603299, 2023).